LOXL1 (lysyl oxidase like 1)
Diseases named in the same sentence as LOXL1 in open-access papers (continued):
Sharing a sentence is not in itself a finding about the gene and the disease.
lung adenocarcinoma (3 papers, 2019 to 2022). A carcinoma that arises from the lung and is characterized by the presence of malignant glandular epithelial cells. "Our results show that the expression of LOXL1 and integrin α11 was correlated in three lung adenocarcinoma patient datasets and that integrin α11 indeed regulated LOXL1 expression in stromal cells." (PMID 31121900, 2019). "A recent study showed a strong correlation between CAF-expressed α11 and LOXL1 expressions in lung adenocarcinoma, and LOXL1 was shown play a critical role in inducing matrix remodeling and collagen fiber alignment, thereby supporting tumor growth and progression in a xenograft model." (PMID 36003785, 2022). "In patients with lung adenocarcinoma, GO terms related to immune activation, including T‐cell proliferation, T‐cell migration, signal transduction and cytokine production, were significantly upregulated in patients with LOXL1‐mutant tumours." (PMID 34105806, 2021). "In a lung adenocarcinoma dataset from The Cancer Genome Atlas (TCGA), we observed a strongly significant correlation between ITGA11 and LOXL1 expression (Spearman r = 0.68, p-value < 0.0001), which we further validated in two other independent patient tumor datasets." (PMID 31121900, 2019).
lymph node metastasis (3 papers, 2020 to 2021). "The clinicopathological analysis showed that high LOXL1 expression was associated with poorly differentiated histological type and lymph node metastasis." (PMID 33095806, 2020). "The clinicopathological analysis showed that the high LOXL1 expression group was significantly associated with a poorly differentiated histological type (Chi-squared test, P < 0.05) and lymph node metastasis (Chi-squared test, P < 0.05)." (PMID 33095806, 2020). "We found that high LOXL1 expression was associated with poorly differentiated histological type, lymph node metastasis, and poor prognosis in GC from the Kyushu validation cohort." (PMID 33095806, 2020). "High LOXL1 mRNA expression was associated with poorly differentiated histological type, lymph node metastasis, and was an independent poor prognostic factor in the Kyushu validation cohort." (PMID 33095806, 2020). "Moreover, LOXL1 is associated with peritoneal dissemination, potentially via promoting EMT in GC cells, and high LOXL1 expression was associated with poorly differentiated histological type, lymph node metastasis, and poor prognosis in GC." (PMID 35126449, 2021). "Furthermore, we performed a multivariate analysis with four variables (LOXL1 expression, depth of tumor invasion, lymph node metastasis, distant metastases) among all eight variables affecting overall survival in univariate analyses in the Kyushu validation cohort." (PMID 33095806, 2020).
melanoma (3 papers, 2018 to 2025). A malignant, usually aggressive tumor composed of atypical, neoplastic melanocytes. "Here, we found that also the expression of LOX, LOXL1, and LOXL3 encoding proteins that crosslink ECM proteins (collagens and elastin) are increased in many melanoma cells and primary melanomas." (PMID 30701028, 2018). "First, we studied the mRNA expression levels of LOX and LOXL1-4 in a panel of melanoma cell lines and primary melanoma cells, as well as in primary human melanocytes, fibroblasts, and endothelial cells." (PMID 30701028, 2018). "In addition to cell lines, we also compared the mRNA expression levels of LOX and LOXL1-4 in clinical tissue specimens of human benign nevi and malignant melanomas, and found LOXL1 (fold 1.6; p = 0.0028) and LOXL2 (fold 2.0; p = 0.00016) to be significantly upregulated in the primary melanomas." (PMID 30701028, 2018).
ocular hypertension (3 papers, 2021 to 2025). Abnormally high intraocular pressure. "Importantly, variants in the LOXL1 gene are associated with high risk for ocular hypertension and PEXG." (PMID 37905384, 2023). "In the eye, Loxl1−/− mice have lens abnormalities, blood-aqueous barrier disruption and elastic tissue dysfunction in the conventional outflow pathway, which leads to ocular hypertension." (PMID 37905384, 2023).
pancreatic ductal adenocarcinoma (3 papers, 2021 to 2023). An infiltrating adenocarcinoma that arises from the epithelial cells of the pancreas. "Moreover, LOXL1 expression is associated with chemoresistance in NSCLC and pancreatic ductal carcinoma." (PMID 35152572, 2022). "Increased LOXL1 was found in pancreatic ductal adenocarcinoma." (PMID 33790946, 2021).
astrocytomas (2 papers, 2022). "Interestingly, there was a progressive increase in CTNNB1, which codes for β-catenin, according to astrocytoma malignancy grade, and its expression correlated significantly with LOXL1 and LOXL3 expression in both LGG-IDHmut and LGG-IDHwt." (PMID 36076905, 2022). "LOXL1, LOXL2, LOXL3, and LOXL4 expression levels were also found to increase progressively in astrocytomas from grades 2 to 4, proving highest in GBM, and significantly higher relative to non-neoplastic brain tissue." (PMID 36076905, 2022). "The progressive gene expression connectivity among LOX, LOXL1, and LOXL3 and matrisome-related genes from LGG-IDHmut, LGG-IDHwt, and through to GBM, reinforce the impact of ECM components contributing for matrix stiffness on the malignant progression and prognosis of astrocytoma." (PMID 36076905, 2022). "Gene expression analysis by quantitative real-time PCR (RT-qPCR) for LOX, LOXL1, LOXL2, LOXL3, and LOXL4 showed increased expression levels in astrocytoma samples compared to non-neoplastic (NN) samples." (PMID 36076905, 2022).
Cirrhosis (2 papers, 2018 to 2023). A chronic disorder of the liver in which liver tissue becomes scarred and is partially replaced by regenerative nodules and fibrotic tissue resulting in loss of liver function. "Moreover, ITGBL1, LOXL1 and PPP4R1 are all significantly enriched in the Ribosome pathway, so these three genes may also influence the formation of cirrhosis by regulating ribosome function." (PMID 37808522, 2023).
Inguinal hernia (2 papers, 2020 to 2025). Protrusion of the contents of the abdominal cavity through the inguinal canal. "We found variants at nine loci to associate with POP; five of which associate at genome-wide significance with POP, three that were previously associated with height (P < 1.4 × 10−5) at TXNDC5 (6p24.3), SLC12A2 (5q23.3) and LOXL1 (15q24.1) and one at WT1 that associates with inguinal hernia (11p13)." (PMID 32184442, 2020).
keratoconus (2 papers, 2022 to 2023). A degenerative, structural disorder of the eye, characterized by a cone-shaped protrusion of the cornea. "Given the relevance of the functional deficiency of LOX enzymes in keratoconus, LOXL1 is proposed as a possible candidate gene." (PMID 37895187, 2023).
lobular carcinomas (2 papers, 2021 to 2022). "Examining the cancer genome atlas (TCGA) patient dataset identified lysyl oxidase like 1 (LOXL1), a collagen modifying enzyme, as being highly expressed in lobular carcinomas." (PMID 36242657, 2022). "In light of our finding that the strong ECM signature as well as the increased LOXL1 expression are lobular carcinoma cell‐intrinsic, we examined LOXL1 transcript expression by in situ hybridization on ILC samples from seven patients with multiple RNAscope probes." (PMID 33616307, 2021). "Thus, LOXL1 is expressed by the lobular carcinoma cells in patient samples." (PMID 33616307, 2021).
normal tension glaucoma (2 papers, 2008 to 2010). "This is also the first study reporting the association of LOXL1 SNPs with normal tension glaucoma." (PMID 18958304, 2008).
Primary glaucoma (2 papers, 2008 to 2010). "However, the allele frequencies of the LOXL1 SNPs in PG/PDS patients were similar to that observed in primary glaucomas." (PMID 18618003, 2008).
pterygium (2 papers, 2019 to 2021). A wedge-shaped fibrovascular lesion arising from the bulbar conjunctiva and extending to the cornea. "As compared with LOX, the relative amount of LOXL1 mRNA was correlated with protein expression and showed a significant increase of approximately two-fold in pterygium as compared with healthy conjunctiva (p < 0.001)." (PMID 34945227, 2021). "In our case, overexpressed LOXL1 mRNA and protein levels were identified in pterygium, but, in the case of LOX, the messenger remained stable and only the protein levels showed a significant increase in pterygium pathology." (PMID 34945227, 2021). "Given that LOXL-1 seems to be necessary more specifically in the crosslinking of TE that participates in the formation, maintenance, and remodeling of elastic fibers, particularly during dynamic processes, the increase of this protein in the ECM of pterygium would be totally justified." (PMID 34945227, 2021).
thyroid cancer (2 papers, 2022 to 2025). "In unpaired samples, the expression levels of COL5A1 and LOXL1 were significantly higher in thyroid cancer than in normal tissues (505 cancer and 59 normal samples), and LYSMD3 levels were significantly lower in thyroid cancer." (PMID 35152572, 2022). "Five survival‐related genes, TMEM63C, COL5A1, LOXL1, ADAMTS2, and LYSMD3 were identified; the expression of COL5A1 and LOXL1 was upregulated in PTC tissues and may be related to OS and PFS of thyroid cancer patients." (PMID 35152572, 2022).
adolescent idiopathic scoliosis (1 paper, 2011). A scoliosis with no known cause arising in adolescent. "We hypothesized that common polymorphisms in the five human lysyl oxidase genes (LOX, LOXL1, LOXL2, LOXL3, and LOXL4) may be associated with the phenotype of adolescent idiopathic scoliosis." (PMID 21740577, 2011).
age-related macular degeneration (1 paper, 2011). Age-related loss of vision in the central portion of the retina (macula), secondary to retinal degeneration. "The role of the LOXL1 polymorphism has been tested in several pathologies including wet and dry age-related macular degeneration and polypoidal choroidal vasculopathy in a Japanese population, Alzheimer disease in a Swedish population, and cardiovascular disease in a Hungarian population." (PMID 22194657, 2011).
astrocytic tumor (1 paper, 2022). A glial tumor of the brain or spinal cord showing astrocytic differentiation. "We speculate that LOXL1, and its interactions with the matrisome-related genes, may be involved in this first step of transformation towards an astrocytic tumor." (PMID 36076905, 2022).
bladder tumor (1 paper, 2016). "However, over expression of the LOX-related enzymes, LOXL1 and LOXL4, in 5637 cells antagonized Ras activation and reduced Erk phosphorylation, suggesting that these enzymes function to suppress bladder tumor growth." (PMID 26968815, 2016).
brain tumors (1 paper, 2020). "Next, we investigated the role of LOXL1 in brain tumor development using LN18-shLOXL1 cells or GSC11-shLOXL1 cells stably expressing luciferase." (PMID 32424143, 2020). "Ki67 staining showed a smaller decrease of proliferated cells in brain tumors composed of U87-LOXL1 cells than U87-Vec cells after IR treatment, indicating overexpression of LOXL1 could counteract the IR efficiency by conferring antiapoptotic activity." (PMID 32424143, 2020). "Thus, LOXL1 may be specifically employed by tumor cells to resist apoptosis and may represent a therapeutic target for treating invasive brain tumors." (PMID 32424143, 2020).
cataract (1 paper, 2016). Partial or complete opacity of the crystalline lens of one or both eyes that decreases visual acuity and eventually results in blindness. "The susceptible PEX gene LOXL1 was hypermethylated in its promoter region and was down- regulated on the mRNA and protein level in Uighur PEX cataract patients." (PMID 27507241, 2016).
colitis (1 paper, 2018). Inflammation of the colon. "We found S4-expressed Lox and Loxl1 blockade attenuated DSS colitis and reduced circulating markers of oxidative stress." (PMID 30270042, 2018). "In S4 cells from DSS colitis, Lox and Loxl1 are induced with high mesenchymal-specific expression." (PMID 30270042, 2018).
diabetic nephropathy (1 paper, 2025). "Consistent with the RNA-seq data, quantitative real-time PCR (qPCR) analysis confirmed a substantial elevation in renal mRNA levels of Lox, Loxl1 and Loxl2 in the diabetic nephropathy model group relative to normal controls." (PMID 41355449, 2025).
emphysema (1 paper, 2021). "Although polymorphisms of LOXL1 in humans have not been associated with POP (OR: 1.147), mice lacking LOXL1 do not deposit normal elastic fibers and thus develop POP or emphysema." (PMID 33413618, 2021).
endometrioid ovarian carcinoma (1 paper, 2020). "When considering endometrioid ovarian carcinoma patients, the mRNA expression levels of LOX, LOXL1, LOXL2, LOXL3, and LOXL4 demonstrated no relation with OS or PFS." (PMID 33058284, 2020).
endothelial dysfunction (1 paper, 2012). In vascular diseases, endothelial dysfunction is a systemic pathological state of the endothelium (the inner lining of blood vessels) and can be broadly defined as an imbalance between vasodilating and vasoconstricting substances produced by (or acting on) the endothelium. "So far there are no reports on correlation between LOXL1 activation and endothelial dysfunction, vascular injury nor vWF/selectins." (PMID 22593709, 2012).
Fabry disease (1 paper, 2025). Fabry disease (FD) is a progressive, inherited, multisystemic lysosomal storage disease characterized by specific neurological, cutaneous, renal, cardiovascular, cochleo-vestibular and cerebrovascular manifestations. "Conversely, genes crucial for ECM integrity and maintenance, including ADAMTS5, LOXL1, COL1A1, and COL6A2, were all down-regulated in the patient hURECs, indicating dysregulated ECM dynamics, as previously observed in Fabry disease." (PMID 40673439, 2025).
Hernia (1 paper, 2025). "LOXL1—an elastin/collagen cross-linking enzyme—shows reduced expression in direct hernia fascia together with increased elastase, implying impaired elastic-fiber integrity and suboptimal cross-link maturation within the load path of the groin." (PMID 41440470, 2025). "In hernia-prone fascia specifically, LOXL1 (a cross-linking enzyme essential for both elastin and collagen maturation) is downregulated, while elastase activity is elevated, a signature of impaired elastic-fiber repair and inferior cross-link maturation within the transversalis fascia load path." (PMID 41440470, 2025).
keloid (1 paper, 2021). An irregularly shaped, elevated mark on the skin caused by deposits of excessive amounts of collagen during wound healing. "In addition to collagen-degrading enzymes, we examined the gene-expression levels of collagen-cross-linking enzymes, such as LOX, LOXL-1, LOXL-2 and LOXL-3, finding that they were substantially upregulated in keloid dermal fibroblasts relative to either normal or hypertrophic dermal fibroblasts." (PMID 33672186, 2021).
leukemia (1 paper, 2022). A malignant (clonal) hematologic disorder, involving hematopoietic stem cells and characterized by the presence of primitive or atypical myeloid or lymphoid cells in the bone marrow and the blood. "The Re trajectory (cluster 5 towards cluster 9) is hallmarked by upregulation of numerous genes required for differentiation, leukemia progression and chemo-resistance, including RACK1, EREG and LOXL1." (PMID 35986270, 2022).
liver steatosis (1 paper, 2024). "Studies have demonstrated that down-regulation of LOXL1 can slow disease progression, and HSC-specific LOXL1 knockout in a mouse model of non-obese NASH attenuated liver steatosis, inflammation, and fibrosis, suggesting that LOXL1 may be involved in HSC activation and fibrogenesis." (PMID 38565287, 2024).
lung squamous cell carcinoma (1 paper, 2019). "In contrast, the correlation in gene expression between ITGA11 and LOXL1 in lung squamous cell carcinoma and between ITGA11 and other LOX family members was not consistent in these three independent datasets." (PMID 31121900, 2019).
mesothelioma (1 paper, 2020). A usually malignant and aggressive neoplasm of the mesothelium which is often associated with exposure to asbestos. "However, four (LOX, LOXL1, LOXL2, LOXL4) and three (LOX, LOXL1, LOXL4) members were present in the mesothelioma (MESO; 87 patients, 239 genes) and ovarian serous cystadenocarcinoma (OV; 427 patients, 209 genes) datasets." (PMID 33383846, 2020).
Microspherophakia (1 paper, 2025). Microspherophakia is a rare congenital anomaly characterized by the abnormal spherical shape of the crystalline lens. "This indicates that Loxl1−/− mice did not have microspherophakia, a phenotype seen in other connective tissue diseases." (PMID 41009782, 2025).
myopia (1 paper, 2025). "Loxl1−/− mice also had deeper ACD compared with wt mice, consistent with the axial myopia phenotype in human patients." (PMID 41009782, 2025).
oral cancer (1 paper, 2022). "A panel of five genes (MMP1, FBLN5, COL5A3, BGN and LOXL1) was useful for predication the successful grafters among oral cancer patients." (PMID 35444950, 2022).
osteoarthritis (1 paper, 2024). A noninflammatory degenerative joint disease occurring chiefly in older persons, characterized by degeneration of the articular cartilage, hypertrophy of bone at the margins and changes in the synovial membrane. "We first investigated LOXL1 expression in normal subjects, degenerative arthritis and rheumatoid arthritis." (PMID 38217541, 2024). "Focusing on LOXL1, which has been little explored in chronic osteoarthritic diseases including rheumatoid arthritis and osteoarthritis, we examined the expression levels of LOXL1 in synovial tissues of patients with chronic osteoarthritis and normal humans using RT-qPCR and western blot methods." (PMID 38217541, 2024).
papillary thyroid carcinoma (1 paper, 2022). "Similarly, papillary thyroid carcinoma (PTC) cells with high LOXL1 expression exhibit more aggressive behavior, in which LOXL1 can be used as a prognostic biomarker for advanced PTC." (PMID 36293126, 2022).
Parkinson disease (1 paper, 2023). A progressive degenerative disorder of the central nervous system characterized by loss of dopamine producing neurons in the substantia nigra and the presence of Lewy bodies in the substantia nigra and locus coeruleus. "In the end, 2 NFRGs (EN1 and LOXL1) were identified as crucial for the development of Parkinson’s disease and the outcome of GBM." (PMID 36825022, 2023). "In the GSE49036 dataset consisting of patients with Parkinson’s disease at different Braak stages, there was significant difference in the expression of EN1, PLOD3 and LOXL1 in the different Braak stages 0 to 6 of Parkinson’s disease." (PMID 36825022, 2023).